TNF (tumor necrosis factor)
Diseases named in the same sentence as TNF in open-access papers (continued):
Sharing a sentence is not in itself a finding about the gene and the disease.
tumor (continued). "These IFNγ-mediated anti-tumor activities could potentially contribute to the increased NPC cell death induced by rhCD137L-MSNs, which may be further enhanced by the additive effects of TNF and FasL." (PMID 41328355, 2026). "Notably, immune‐related pathway activities, including TNFα signaling, interferon pathways, and IL6‐JAK‐STAT3 signaling, were reduced in stiff tumors, suggesting a diminished immune response potentially from altered structural characteristics of the tumor." (PMID 40988561, 2026). "Although TNF-α production by intratumoral dendritic cells showed no major differences, rBCG-treated mice exhibited significantly elevated CD86 expression in tumor-associated macrophages, suggesting improved costimulatory capacity within the tumor niche." (PMID 41522339, 2026). "Cytokines such as tumor necrosis factor-α (TNF), interleukin, and transforming growth factor-beta (TGF-β) modulate the expression of various ECM molecules and promote host cell differentiation, thereby shaping a stroma conducive to tumor survival and metastasis." (PMID 41787034, 2026). "We exposed the TIL products for 6–7 h to autologous tumor digest, and we measured the expression of the activation marker CD137 (4-1BB) indicative of TCR triggering, the degranulation marker CD107a, and TNF and IFNγ required for effective antitumoral responses." (PMID 40897471, 2025). "CD8+ cytotoxic T lymphocytes eradicate tumor cells through two cooperative mechanisms: the perforin/granzyme pathway induces rapid lysis of target cells, while secretion of cytokines such as IL-2, IFN-γ, and TNF-α establishes a proinflammatory milieu that sustains long-term cytotoxic activity." (PMID 41320679, 2025). "In cancer patients, the tumor itself, treatment side effects, and psychological stress can all serve as chronic stressors, continuously activating the innate immune system and HPA axis, leading to elevated levels of pro-inflammatory cytokines (such as TNF - α, IL-6) and cortisol." (PMID 41480347, 2025). "Similarly, targeting the secretion of pro-inflammatory cytokines like TNF-α or IL-6 from adipocytes may alleviate inflammation within the TME and enhance anti-tumor immune responses." (PMID 41200178, 2025). "These functions include the secretion of TH1 cytokines such as TNF-α and IFN-γ, the release of cytolytic granules containing granzymes A and B and perforin, and the expression of death receptor ligands like TRAIL and FASL, which can induce tumor cell apoptosis." (PMID 40148988, 2025). "To further verify the relationship between IL34 and tumor cells, we localized tumor subgroups in the spatial transcriptome and found that the spatial location of the tumor with high IL34 expression was close to the TNF-α+ TAMs with high TNF and CCL2 expression." (PMID 39865310, 2025). "To see whether similar results are found in M1 macrophages polarized by stimuli other than IFNγ + LPS and M2 macrophages by IL-4 or TGF-β1, we stimulated the macrophages with a tumor conditioned media of 2D- (2D TCM) or 3D-cultured tumor cells (3D TCM), IFNγ alone, TNFα, IL-4 or TGF-β1." (PMID 40050422, 2025). "However, current literature indicates that the interaction between HMGCR and TNF-α is not uniform across different tumor types and tumor immune microenvironments, but rather exhibits significant variability." (PMID 41450917, 2025). "JUNB signaling can be regionally repressed through macrophage-secreted TNF-α, destabilizing favorable CLA-like state and inducing T cell exclusion, which highlights the important role of the single cytokine TNF-α in shaping an immunosuppressive TiME and tumor aggressiveness." (PMID 39762215, 2025). "Finally, tumor-promoting inflammation was also identified as a relevant enabling mechanism, specifically, the presence of proinflammatory cytokines such as IL-6 (SMD = −1.07, 95% CI = −1.86 to −0.28, p = 0.008) or TNF-α." (PMID 40805130, 2025).
tumor (continued). "Thus, TNF-α-dependent macrophage recruitment appeared to be halted, leading to a less immunosuppressive TiME in GEM plus anti-TNF-α-treated PDAC tumors, which highlights the important role of TNF-α in shaping the immune landscape to aid tumor growth and survival." (PMID 39762215, 2025). "The levels of the myeloid cell-secreted cytokines tumor necrosis factor (TNF), C–C motif chemokine ligand 3 and 4 (CCL3 and CCL4), and monocyte chemoattractant protein- 4 (MCP- 4) increased significantly with treatment, while Galectin- 9, involved in tumor immune evasion, decreased." (PMID 40310569, 2025). "This shift away from IFN-γ and TNF-α production suggests that MAIT cells in the breast cancer microenvironment may contribute to tumor-promoting inflammation rather than effective antitumor immunity." (PMID 40746558, 2025). "Mediators of the Th2 pathway also may divert tissue immunity away from an anti-tumor Th1 response (i.e., IgG1, TNF-α) and toward an IgE response against allergens, and not tumor antigens through “inappropriate Th2 immune skewing”." (PMID 40620564, 2025). "Again, analysis on tumor tissue (injected and non-injected) could provide knowledge on virus-induced changes and the viral production of TNF and IL-2." (PMID 40107242, 2025). "In the tumor microenvironment, for example, IL-8, IL-12, and tumor necrosis factor (TNF) can recruit immune cells such as M1-like macrophages, enhancing the removal of detrimental senescent and aging cells that are consistent with the tumor suppression effect of senescence." (PMID 40563707, 2025). "Furthermore, the TNFα and inflammatory response pathways were also upregulated, not only demonstrating the cytotoxic effect of GEM but also the possible immune effect of GEM on the tumour." (PMID 41148819, 2025). "The resulting hyper-activated CD8+ T cells produce IL-2, interferon (IFN)γ, tumor necrosis factor (TNF)α, and GM-CSF and efficiently lyse autologous tumor cells via recognition of the same peptides this time presented to them in the context of the tumor’s MHC class I molecules." (PMID 41374956, 2025). "Traditional studies in solid tumors have shown that CD4 TH cells sustain anti‐tumor activity by directing other leukocytes, enhancing tumor‐antigen presentation, and directly inhibiting tumor proliferation via interferon gamma (IFN‐γ) and tumor necrosis factor alpha (TNF‐α)." (PMID 40571973, 2025). "Furthermore, CD4+ T cells could inhibit tumor cell cycle progression and activate pro-inflammatory signaling pathways involving TNF and INF-γ, effectively inducing tumor cell regression." (PMID 39859524, 2025). "It has been demonstrated that tumor cells release inflammatory cytokines (IL-6, IL-1, TNF-α), chemokines (CCL2, CCL5, CCL15, CCL26), and growth factors (TGFβ), which ultimately recruit BMDCs such as myeloid-derived suppressor cells (MDSCs) and create a favorable niche for tumor development." (PMID 41383620, 2025). "It has been found that caspase‐G and TNF secreted by neutrophils can induce cancer cell migration, and caspase‐G has the effect of hydrolyzing the ECM, which can increase the flexibility of cancer cell movement, thus enabling the tumor to gain invasive ability." (PMID 40979214, 2025). "Furthermore, the suppression of TNFα and IL6 suggests a diminished inflammatory response, which may impair T-cell effector function and cytokine-mediated anti-tumor immunity." (PMID 40407494, 2025). "Additionally, CD8+ T cells from both tumor and non-tumor tissues demonstrated comparable capacities to produce anti-tumor cytokines upon PMA and ionomycin stimulation, including IFN-γ, TNF-α, and IL-2, despite the higher proportion of CD103N cells in the tumor tissue." (PMID 41182407, 2025). "Moreover, PGFP significantly upregulated the expression of TNF‐α and IFN‐γ in T cells compared to treatment with PTPR alone, highlighting its potential to enhance anti‐tumor immune responses." (PMID 40788220, 2025).
tumor (continued). "By secreting cytokines such as TNF-α, interleukin-12 (IL-12), and interferon-gamma (IFN-γ), N1 neutrophils facilitate the polarization and activation of cytotoxic T cells and NK cells, creating a pro-inflammatory microenvironment that promotes tumor immune surveillance." (PMID 40486595, 2025). "CSCs themselves modify the tumor microenvironment to replicate the conditions of stem cell niches, promote epithelial-mesenchymal transition (EMT) in nearby tumor cells, and alter the microenvironment of distant tissues by secreting factors such as VEGFA, LOX, TGFβ, and TNFα to promote metastasis." (PMID 40813991, 2025). "Silibinin inhibits tumor growth through immunomodulatory activities, such as regulating immune cells (Tregs, macrophages, DCs, NK cell), inhibiting inflammatory cytokines (IFN-γ, IL-2, IL-6, IL-10, IL-12, TNF-α, and TGF-β), and modulating immune check points (PD-L1 and PD-1)." (PMID 40490812, 2025). "Importantly, TNF‐α concentrations only increased in mice that displayed robust tumour growth and not in those mice in which tumours regressed or did not develop at all in the first place." (PMID 40172096, 2025). "Moreover, after HA@CD36i‐TR@siSCD1 treatment, we observed that in both LFD‐fed and HFD‐fed mice, the intratumoral CD8+/CD4+ T‐cell ratios increased significantly, with decreased Treg cells and increased TNF‐α and IFN‐γ levels, indicating that PCa transformed from a “cold” tumor to a “hot” tumor." (PMID 39736148, 2025). "However, no patients receiving LCL161 had an OR in the study, possibly due to the lack of tumor sensitivity to TNF." (PMID 41408891, 2025). "And M1 macrophages can produce tumor necrosis factor-alpha (TNF-α) and pro-inflammatory cytokines such as IL-6, IL-12, and IL-18, express high levels of Major Histocompatibility Complex Class II (MHC II) and CD68, and inhibit tumor cell growth and proliferation." (PMID 40131539, 2025). "Elevated levels of pro-inflammatory cytokines, including TNF-α, IL-6, and IL-27, were detected in ALL patients, reflecting abnormal immune activation and suggesting a potential role in disease progression through tumor growth, immune evasion, or enhanced cytotoxicity." (PMID 41254398, 2025). "Notably, the tumor TNF-α signaling via NF-κB pathway showed negative correlation with serum TNF-α levels." (PMID 40536814, 2025). "Moreover, the neutralization of IFNγ, but not TNFα, significantly attenuated birinapant-induced immune-dependent anti-tumor activity." (PMID 40057483, 2025). "When the tumor was irradiated, pyroptosis was induced by activated caspase-1 cleavage of GSDME, which significantly increased the production of ROS, and the levels of TNF-α and IFN-γ were significantly elevated, promoting the death of tumor cells by T cells and other killer immune cells." (PMID 40698137, 2025). "Functional analyses confirmed that TG7 promotes tumor cell proliferation, and that its silencing using DsiRNA3 led to a dose-dependent reduction in cell viability, accompanied by the upregulation of pro-inflammatory cytokines IL6 and TNFα, as well as the apoptotic marker CASP3." (PMID 41425727, 2025). "Alongside TNF-α, IL-6 contributes significantly to amplifying NF-κB-driven inflammation by activating the JAK/STAT3 pathway, which can subsequently boost NF-κB signaling This establishes another positive feedback loop that sustains chronic inflammation and supports tumor growth." (PMID 39949765, 2025). "Proinflammatory cytokines such as interleukin (IL)-6 and tumor necrosis factor-alpha (TNF-α) can influence immune checkpoint activity and sleep regulation, indicating a mechanistic link through shared neuroimmune and inflammatory pathways that shape tumor immunity and sleep physiology." (PMID 41470133, 2025).
tumor (continued). "Th1 cells are crucial for tumor elimination as they produce TNF-α and IFN-γ, which stimulate the recruitment and activation of cytotoxic CD8+ T cells (CTLs), NK cells, and monocytes to the tumor microenvironment, while also negatively regulating tumor-promoting Th17 cells." (PMID 39911389, 2025). "In addition, GOS inhibits TNF-induced MMP9 expression: Tumor necrosis factor (TNF) can stimulate the production of matrix metalloproteinase 9 (MMP9), an enzyme that degrades the extracellular matrix and facilitates tumor invasion and metastasis." (PMID 40002373, 2025). "In the present study, we demonstrated that pharmacological inhibition of soluble TNF/TNFR1 signaling by XPro1595, but not TNFR1 gene deletion, significantly reduced PNI-associated mechanical hypersensitivity, mitigated tumor progression, and improved motor performance primarily in female mice." (PMID 41294802, 2025). "By attenuating upstream mediators such as TNFα and VEGFα, and downstream effectors like COX-2 and MMP-2, HA extract and L-NAME co-treatment effectively disrupt multiple nodes of the oncogenic network, potentially limiting both the expansion and the invasive capacity of tumor cells." (PMID 40179064, 2025). "Cytokines such as IFN-γ and TNF-α are key mediators of antitumor immunity, with IFN-γ known to enhance the antigen presentation and cytotoxicity of immune cells, while TNF-α plays a pivotal role in inducing apoptosis in GBM cells and modulating the tumor microenvironment." (PMID 39753685, 2025). "Regarding the cytokine profile, notable modulations were observed in the levels of IL-1β, IL-4, IL-6, IL-10, IL-17A, and TNF-α, particularly in the FMT groups, indicating an influence on the local immune response that could contribute to shaping the tumor microenvironment." (PMID 41614846, 2025). "Furthermore, SZP NPs induced ICD in the IRFA subcutaneous H22 model by promoting dendritic cell maturation in residual tumors, enhancing CD4+ and CD8 + T cell infiltration, and increasing anti‐tumor cytokine secretion (IFN‐γ, TNF‐α) and effector memory T cells." (PMID 40529859, 2025). "Macrophages are the primary producers of numerous molecules that facilitate tumor angiogenesis, such as VEGFA, CXCL8 (chemokine (C-X-C motif) ligand 8), PlGF (placental growth factor), IL-1β (interleukin-1 beta), IL-6 (interleukin-6), TNF (tumor necrosis factor), MMPs, and cathepsins." (PMID 40940953, 2025). "Additionally, in CMT-N7 cells, TNF/MAPK inflammatory pathway-related genes such as CXCL10 and MECOM were significantly upregulated following W6134 and XY018 treatment, exhibiting favorable anti-tumor effects, which aligns with previous findings." (PMID 40805064, 2025). "In addition, the expression of several pro-inflammatory cytokines and chemokines such as IL-1β, IL-22, TNF-α, CXCL1, CXCL2, CCL17 and CCL20 were reduced in IL-38KO mice, suggesting that IL-38 promotes tumour growth and development in cSSC through promoting an inflammatory tumour environment." (PMID 40057603, 2025). "Furthermore, while many γδT cells exert potent anti-tumor effects through the production of pro-inflammatory cytokines like IFN-γ and TNF-α, certain subsets, including IL-10-producing γδT cells, have been identified as immunosuppressive, particularly in solid tumors." (PMID 40226616, 2025). "In addition, activated T cells secrete Cytokines such as IFN-γ and TNF-α, which further recruit additional effector T cells (e.g., CD8+ T cells) and natural killer (NK) cells into the Tumor Microenvironment, contributing to the establishment of long-lasting anti-tumor immune memory." (PMID 41333481, 2025). "Mechanistically, TNFRSF18+ T cells are involved in immune regulation through the TNF signalling pathway, but TNFRSF18 expression decreased with tumour progression, suggesting that the tumour microenvironment may inhibit the apoptosis and immune activation function of exhausted T cells." (PMID 40770837, 2025).
tumor (continued). "Particularly, intravesical instillation of VB-85247 induced elevated gene expression in the tumor-bearing bladders for IFNβ, CXCL10, CCL5, IL6, and TNFα at 4 hours after treatment, with the fold-induction of gene expression in the order of IFNβ > CXCL10 > CCL5 > IL6 > TNFα." (PMID 39700406, 2025). "Compared with CAR-NK cells co-expressing IL-15, CAR-NK cells co-expressing IL-21 exhibited significantly increased IFN-γ, TNF-α and Granzyme B production, as well as degranulation, in response to CD19+ Raji lymphoma cells, resulting in enhanced cytotoxic activity upon repetitive tumor stimulation." (PMID 40176196, 2025). "Notably, cerebrospinal fluid and peripheral blood monocytes are major sources of IL-6, IL-18 (a chemokine subclass), and TNF-α (which selectively targets tumor cells without significant toxicity to normal cells)." (PMID 41458177, 2025). "In this synergistic setting, the frequency of IFN-γ+ and TNF-α+ CD4+ T cells in the SFB+ B16-3340 group showed extremely strong negative correlations with tumor burden (r = -0.9057 and r = -0.9742, respectively), indicating a direct linear relationship between Th1 responses and tumor eradication." (PMID 41441899, 2025). "CRP, ESR, and fibrinogen all had small regression coefficients (each β close to 0, p > 0.5), indicating that systemic inflammation measures did not contribute additional explanatory power for TNF-α levels beyond what the tumor markers and stage already provided." (PMID 40299527, 2025). "Although the major catabolic drivers of muscle wasting in cachectic patients are not fully characterized, a number of tumor-derived inflammatory cytokines have been shown to promote cancer cachexia, such as tumor necrosis factor α (TNFα) and interferon-γ (IFN- γ)." (PMID 41392310, 2025). "First, tumor cells can secrete various cytokines (such as IL-6, IL-10, and TNF-α), and the changes in the expression of these cytokines not only affect the infiltration and activity of leukocytes but also promote alterations in the biochemical properties of surrounding fibroblasts." (PMID 40008000, 2025). "Notably, tumour cells were washed after TNF‐α treatment to ensure that TNF‐α did not act on endothelial cells during the adhesion assay." (PMID 40488391, 2025). "Although no tumor cells were detected in the hypothalamus, unbiased profiling under testosterone-neutralizing conditions revealed increased signaling of interleukin-1 beta (IL-1β) and tumor necrosis factor (TNF)." (PMID 41221269, 2025). "Animal models and clinical inferences support that regional blocks may attenuate surgical‐induced pro‐inflammatory mediators (e.g., IL‐6, TNF‐α, vascular endothelial growth factor [VEGF]), potentially impacting postoperative tumor spread and inflammatory index." (PMID 40958235, 2025). "While generally cytotoxic, Tc1 cells produce cytokines such as interferon-γ (IFN-γ), tumor necrosis factor-α (TNF-α), and granzyme B, which may exert immunomodulatory effects and, under certain conditions, support tumor progression through mechanisms that resemble those of CD4+ helper T cells." (PMID 40723153, 2025). "Next, we found the expression of TNF-α, IFN-γ and CD107a representative of cytotoxicity in CD8+ T cells were all elevated in the the ABCC4-KO group, implying that genetic ablation of ABCC4 in tumor cells could restore the anti-tumor effects of CD8+ T cells." (PMID 39247809, 2024). "Our study found a significant decrease in IL-6, IL-1β, IL-17A, and TNF-α levels in mice after L.p CMU-Pb-L5 intervention, indicating that L.p CMU-Pb-L5 intervention could reduce inflammatory cytokine levels in vivo and slow CRC tumor growth." (PMID 39439459, 2024). "The mode of action of γδ T cells in an anti-tumor response comprises direct cytolytic activity via NKG2D, FcyRIII, Fas/Fas-ligand, DNAM-1 receptor-ligand interaction and the TNF related apoptosis inducing ligand (TRAIL) pathway resulting in production of perforins, granzymes, IFN-γ and TNF-α." (PMID 38426099, 2024).